RUNX2 (RUNX family transcription factor 2)
Diseases named in the same sentence as RUNX2 in open-access papers (continued):
Sharing a sentence is not in itself a finding about the gene and the disease.
breast carcinoma (continued). "We illustrated the regulation of the expression of miR-10a/b by RUNX2 in breast cancer cells." (PMID 25266482, 2014). "Interestingly, it has been shown that ERα interacts with RUNX2 in MCF7 breast cancer cell line, and the MC3T3-E1 pre-osteoblast cell line, and that this interaction was estrogen dependant, and resulted in the inhibition of RUNX2 activity." (PMID 25313644, 2014). "Runx2 was also reported to be highly expressed in breast cancer with poor clinical outcomes." (PMID 25266482, 2014). "We assessed expression of RUNX2 in a cohort of human breast cancers using a tissue array (TMA-1)." (PMID 24626992, 2014). "Interestingly, it has been reported that Runx2 is directly phosphorylated by Akt that increases Runx2 DNA binding activity in breast cancer cells." (PMID 24479521, 2014). "RUNX2/Smad 3 interaction stimulated collagen 3 expression in breast cancer cells." (PMID 22966907, 2012). "Contrary to the tumour suppressor-like behaviour of RUNX2 that has been described by previously published studies of the protein, several recent studies have identified RUNX2 as potentially having a direct role in promoting neoplasia, particularly in prostate and breast cancers." (PMID 21197465, 2011). "The protein is also important for metastatic bone disease of prostate and breast cancers, while RUNX2 may have both tumor suppressive and oncogenic roles in bone morphogenesis." (PMID 21197465, 2011). "To assess whether expression of RUNX2 is regulated with respect to cell growth in MDA-MB-231 breast cancer cells, we performed serum starvation and stimulation experiments." (PMID 21029421, 2010). "Here, we addressed whether the functional relationship between cell growth and RUNX2 gene expression is maintained in breast cancer cells." (PMID 21029421, 2010). "Such compounds may also be able to disrupt the Runx2/CBFβ interaction in metastatic breast cancer cells." (PMID 20591170, 2010). "Furthermore, RUNX2 levels are elevated upon cell growth inhibition in breast cancer cells, but cell growth is only marginally enhanced upon RUNX2 depletion by RNA interference." (PMID 21029421, 2010). "The Runx2/CBFβ interaction might therefore represent a viable therapeutic target in metastatic breast cancer." (PMID 20591170, 2010). "The main finding is that RUNX2 is required for cell motility of breast cancer cells." (PMID 21029421, 2010). "In this study, we examined how RUNX2 levels are modulated with respect to cell growth, as well as whether RUNX2 controls the metastatic properties of breast cancer cells in culture." (PMID 21029421, 2010). "Furthermore, the angiogenesis-inhibiting effects of emodin in breast cancer cells may be attributable to the downregulation of RUNX2 transcriptional activity." (PMID 38430423, 2024). "Therefore, NGR1 could be a potential drug for the treatment of breast cancer, while RUNX2 is a potential target for the treatment of breast cancer, offering the possibility of developing more effective therapeutic strategies." (PMID 38885076, 2024). "Also, we confirmed that RBM5-AS1 could be upregulated by RUNX2 overexpression, and RUNX2 expression could be induced by hypoxia in breast cancer cells." (PMID 35110544, 2022). "However, the role of RUNX2 in breast cancer metastasis remains poorly understood." (PMID 35534547, 2022). "Recent studies utilizing breast cancer cell lines with MAPK mutations or expressing mutant RAS produced several key findings which suggest that MAPK mutation contribute to autophagy dysregulation and show a similar phenotype to that of aberrant Runx2 expression." (PMID 34503118, 2021). "Moreover, RUNX2 overexpression in the MCF7 breast cancer cell line induced EMT pathways." (PMID 33375067, 2020). "And TGF-β could upregulate Runx2 to promote breast cancer metastasis." (PMID 30930692, 2019).
breast carcinoma (continued). "Since Runx2 directly regulated Fgfr2 and the knockdown of Fgfr2 was effective for inhibiting the proliferation of osteoblast progenitors, the regulation of FGFR2 by RUNX2 may also play an important role in the development and progression of some breast cancers by enhancing cell proliferation." (PMID 30202094, 2018). "Finally, we confirmed the negative association of low ANCR expression and high RUNX2 expression in breast cancer samples." (PMID 28978036, 2017). "In summary, our data demonstrated that the osteomimetic feature of breast cancer with ectopic co-expression of BRGs is obtained from the epithelial cancer cells that undergo stromal cell-induced EMT followed by BMP2-induced transcriptional activation function of RUNX2 in the tumor microenvironment." (PMID 27806311, 2016). "During these processes, runt-related transcription factor 2 (RUNX2) functioned as a master mediator by suppressing or activating the transcription of BRGs that underlie the dynamic antagonism between the TGF-β/SMAD and BMP/SMAD signaling pathways in breast cancer cells." (PMID 27806311, 2016). "However, genome-wide expression profiling of breast cancer showed that RUNX2 attenuates the effect of estradiol on gene expression and colony formation by tumor cells, implying that RUNX2 may possess tumor suppressor properties in breast cancer." (PMID 27007162, 2016). "Thus, RUNX2 functions as a master mediator during the transformation of epithelial breast cancer cells into ostomimetic cells under CAF/BMP2 induction, and the expression of BRGs was repressed in the TGF-β/SMAD/RUNX2 signaling pathway, but induced in the BMP/SMAD/RUNX2 signaling pathway." (PMID 27806311, 2016). "However, some data of RUNX2 expression in breast cancer are inconsistent." (PMID 26404249, 2015). "The role of RUNX2 in breast cancer may be related to its role in normal mammary gland development." (PMID 26404249, 2015). "Since β-catenin is a common regulator of RUNX2 and cyclin D1, and its expression correlates with ER-β receptors in breast cancer cells, it may be considered as another important element of RUNX2-related pathways in breast cancer development." (PMID 26404249, 2015). "This may help to explain the lower expression of RUNX2 in ER + breast cancer than ER- tumors." (PMID 25266482, 2014). "Recently, Runx2, an essential transcription factor in the regulation of mesenchymal cell differentiation into the osteoblast lineage and proper bone development, is also well-recognized for its expression in breast cancer cells promoting osteolytic bone metastasis." (PMID 26237148, 2013). "However, unlike its normal activity in osteoblasts and osteoprogenitor cells, RUNX2 levels do not appear to be critically linked to cell proliferation in MDA-MB-231 breast cancer cells." (PMID 21029421, 2010). "However, our current findings are certainly consistent with prior work showing that RUNX2 may promote the metastatic potential of breast cancer cells by modulating invasiveness and osteolytic properties." (PMID 21029421, 2010). "By downregulating the activity of the Runx2 transcription factor and restraining the binding of Runx2 to the MMP‐13 promoter sequence, it exhibits anti‐breast cancer activity." (PMID 40008240, 2025). "For example, in breast cancer, RUNX2 was identified as a key transcription factor that regulates ITGBL1 expression, promoting the formation of osteomimetic breast cancers and metastasis to bone." (PMID 40287769, 2025). "Meanwhile, TRIM21 inhibits the transcription of runx family transcription factor 2 (RUNX2) by regulating the degradation of set domain containing 7/9 (SET7/9), thereby inhibiting the malignant phenotype in breast cancer." (PMID 39154024, 2024). "In a tumor derived from human breast cancer stem cells grown in a mouse mammary fat pad, the expression of RUNX1 inhibits and the expression of RUNX2 and vimentin enhances the tumor growth." (PMID 38630262, 2024).
breast carcinoma (continued). "The results showed that NGR1 was able to inhibit the expression level of RUNX2 and suppress the AGE/PAGE signaling pathway in breast cancer cells." (PMID 38885076, 2024). "Our study showed that in breast cancer cells NGR1 inhibits the RUNX2 AGE signaling pathway, induces Fe2+ accumulation, enhances intracellular oxidative damage, and thus induces ferroptosis slowing down breast cancer cell proliferation." (PMID 38885076, 2024). "In MDAPSF, the expression of RUNX2 and osteocalcin was detected, demonstrating that stiffness of the PSF hydrogel of about 13 kPa alone can induce the transformation of breast cancer cells into osteoblast-like cells after just three days of growth." (PMID 39684779, 2024). "These include EMT (TWIST1, SNAIL1, RUNX1, RUNX2, HIF1, and NOTCH1), breast cancer maintenance (OCT4, SP1, GATA1, ATF1, FOXO3a, ELK1, VDR, and NRF1), pro-metastatic responses (SMAD2/3, HNF1a, GLI1, NANOG, YY1, MYB1, and AP1), and immune modulation (STAT1/3)." (PMID 38398186, 2024). "Consistent with that report, the depletion of RUNX2 by siRNA inhibited proliferation, as determined by a 5-ethynyl-20-deoxyuridine (EdU) assay, in MDA-MB-231 and SUM159 breast cancer cells." (PMID 37108164, 2023). "Runx2 expression is found in the breast cancer cell line (MDA-MB-231) and Runx2 silencing revealed that it is essential for autophagy." (PMID 36831154, 2023). "RUNX2 with CBFβ has been deemed critical for the expression of Osteopontin/IBSP, IL11 and GM-CSF/CFS2 in metastatic breast cancer cells." (PMID 36831308, 2023). "As Runx2 and Rictor play key roles in angiogenesis, the expression of VEGF was also assessed in breast cancer cells after treatment with miR-218 containing exosomes." (PMID 37968694, 2023). "CADD522 negatively regulated RUNX2 target gene transcription including MMP13, VEGF and SLC2A1 in breast cancer cells." (PMID 36936386, 2023). "These experiments supported a model where tRF-GlyTCC suppresses CS progression by downregulating RUNX2 translation; by YBX1 displacement according to the mechanism of action revealed in breast cancer." (PMID 36936386, 2023). "mRNA expression of target genes (Runx2 and Rictor) in MDA-MB-231 breast cancer cells was evaluated by qPCR." (PMID 37968694, 2023). "ZIC2 can transcriptional regulates Src, lncRNA SNHG12, Axin2, Runx2, OCT4, STAT3, PAK4 expression in non-small cell lung cancer, endometrial cancer, colon cancer, ccRCC, lung adenocarcinoma, liver cancer, and breast cancer 15, 28, 36-41." (PMID 37496990, 2023). "In breast cancer, ABL phosphorylates RUNX2 through direct binding, activating its expression through its SH2 domain in a kinase-activity-dependent manner, and the activation the bone morphogenetic protein (BMP)-SMAD pathway, promoting tumor cell invasion." (PMID 36551878, 2022). "This study founded that the expression of RUNX2 was positively related to the immune infiltration of CD4+ T cells, CD8+ T cells, B cells, neutrophils, DC cells, and macrophages in the breast cancer microenvironment." (PMID 36092942, 2022). "Thus, RUNX2 and PPARα may be potential therapeutic targets for breast cancer bone metastasis." (PMID 35534547, 2022). "The chemotactic migration assay and cancer cell–bone matrix adhesion assay indicated that depletion of RUNX2, MTA1, or CUL4B hampered breast cancer cell metastasis to the bone, while overexpression of RUNX2, MTA1, or CUL4B resulted in the opposite trend." (PMID 35534547, 2022). "It has also been reported that Runx2 negatively regulates SIRT6 expression at both the transcriptional and posttranslational levels in breast cancer." (PMID 34793336, 2022). "We demonstrate that the RUNX2/NuRD(MTA1)/CRL4B complex promotes the proliferation, invasion, tumorigenesis, bone metastasis, cancer stemness of breast cancer in vitro and in vivo." (PMID 35534547, 2022).
breast carcinoma (continued). "The authors suggest reduced expression of Runx2 and related target genes, including IL-11, MMP13, and PThrP, in breast cancer cells in the presence of miR-135 and miR-203 as a working mechanism." (PMID 35158995, 2022). "To determine how RUNX2 regulated breast cancer cell growth, we performed RNA sequencing (RNA-seq) experiments in MDA-MB-231 cells using siRNA against RUNX2." (PMID 35534547, 2022). "In breast cancer, the positive regulation of metastasis through the ABL/RUNX2/MMP13 axis has been reported." (PMID 35805994, 2022). "In order to further elucidate the physical and functional interactions among RUNX2, NuRD(MTA1), and CRL4B, we investigated the role of the RUNX2/NuRD(MTA1)/CRL4B complex in terms of EMT, stemness, and bone metastasis of breast cancer." (PMID 35534547, 2022). "Our results indicated that RUNX2/NuRD(MTA1)/CRL4B complex suppressed invasion, migration, and bone metastasis of breast cancer cells through inhibiting PPARα." (PMID 35534547, 2022). "Thus, we investigated whether RUNX2 or MTA1 affect stem-like phenotypes in breast cancer cells." (PMID 35534547, 2022). "Consistent with the bioinformatics analysis, the expression of RUNX2 was highest in the RUNX family in clinical breast cancer samples and cell lines; Moreover, RUNX2 was overexpressed, while RUNX1 and RUNX3 were decreased in breast cancer tissues." (PMID 35534547, 2022). "In order to gain further support for the notion that the RUNX2/NuRD(MTA1)/CRL4B complex promotes the EMT and bone metastasis of breast cancer cells through the transcriptional repression of target genes, indicated experiments were performed." (PMID 35534547, 2022). "RUNX2 interacts with TAZ to regulate oncogenic soluble E-Cadherin levels and tumorsphere formation in breast cancer cells." (PMID 34831147, 2021). "We found that the methylation level of RUNX3 in breast cancer is completely opposite to that of RUNX1 and RUNX2." (PMID 34485309, 2021). "We found that the methylation level changes of RUNX2 and RUNX3 had opposite effects on immune cell infiltration in breast cancer." (PMID 34485309, 2021). "We also analyzed the relationship between the expression levels of RUNX2/RUNX3 and the infiltration of immune cells in BRCA-basal, BRCA-HER2, and BRCA-luminal breast cancer subtypes." (PMID 34485309, 2021). "An example can be seen in breast cancer bone invasion, whereby miR-301a-d regulates DKK-1, RUNX-2 and ITGA5 genes, which are involved in osteogenesis, leading to breast cancer osteomimicry." (PMID 34680611, 2021). "Treatment of breast cancer cells with CADD522 reduced viability and clonogenicity while also suppressing transcriptional activity of Runx2." (PMID 34503118, 2021). "We showed that RUNX2-mediated MMP13 expression lies downstream of ABL and that depletion of ABL in breast cancer cells inhibits invasive ability." (PMID 34136397, 2021). "Taken together, our data suggest that SET7/9 has a promoting role via the regulation of RUNX2, whereas TRIM21-mediated SET7/9 degradation acts as an anti-braking system in the progression of breast cancer." (PMID 32102992, 2020). "Knockdown of ATF-3 expression in MDA-MB231 breast cancer cells decreases cell number, cell migration, and the expression levels of invasive and metastatic genes, such as MMP-13 and Runt-related transcription factor 2 (Runx2)." (PMID 32922364, 2020). "The intracellular domain of CD44 can act as a co-transcription factor for RUNX2, inducing MMP-9 expression in breast carcinoma cells." (PMID 32204402, 2020). "Specifically, RUNX2 has been shown to regulate genes (e.g., MMP2 and MMP-9) that are involved in metastasis-related events of prostate and breast cancer cells." (PMID 31331331, 2019). "RUNX2 belongs to the RUNX family, plays a role in several tumor tissues, including pancreatic cancer, breast cancer, ovarian epithelial cancer, prostate cancer, and osteosarcoma." (PMID 31832019, 2019).
breast carcinoma (continued). "In summary, our experiments discover that lncRNA-NORAD is up-regulated in breast cancer tissues and cells, which promotes the breast cancer malignant progression via TGF-β signaling pathway and potentially related to RUNX2." (PMID 30930692, 2019). "Next, we stained the tibia of mice injected with an admix of MDA-MB-231GFP/Luc2 human breast cancer cells plus MC3T3-E1 murine osteoblasts using antibodies for FOXN1, to show the population of injected MC3T3-E1 cells, and RUNX2 a unique marker of osteoblasts." (PMID 30813947, 2019). "Compared to untreated breast cancer cells, treated breast cancer cells increased their expression of osteoblast cadherin CDH11, RUNX2, osteonectin (SPARC), the bone matrix-remodeling protein periostin, as well as a defined set of “bone-related genes”." (PMID 29867053, 2018). "For example, estradiol antagonizes the pro-metastatic activity of RUNX2 in vitro, and inhibits RUNX2-induced EMT and invasiveness of breast cancer cells." (PMID 28978036, 2017). "Since opposing effects of AKT1 and AKT2 were described in breast cancer cell migration, AKT1 suppressing invasion and AKT2 enhancing it, we analyzed phosphorylation of AKT1 and AKT2, in addition to T308 in the RUNX2 knocked down melanoma cell lines." (PMID 27102439, 2016). "The indirect regulation of RUNX2 on the PI3K/AKT signaling pathway has been documented in prostate and breast cancer cells." (PMID 26204939, 2015). "RUNX2 induces EMT, with increased expression of the EMT-related transcription factor SNAI2 and decreased expression of E-cadherin in breast cancer cells." (PMID 26204939, 2015). "We also link RUNX2 expression to WNT signalling activation in normal mammary and breast cancer mouse models." (PMID 26489514, 2015). "This study establishes RUNX2 as an AKT substrate and an important mediator of PI3K/AKT signaling in breast cancer." (PMID 26204939, 2015). "Expression of the double or triple mutants of RUNX2 in breast cancer cells reduces the mRNA levels of two metastasis-related target genes, MMP9 and MMP13, and reduces the RUNX2-dependent invasive potential of breast cancer cells." (PMID 26204939, 2015). "In response to TGFβ, RUNX2 interacts with SMAD3 and JUNB at the distal runt domain (RD) site of the MMP13 (collagenase-3) promoter in MDA-MB-231 breast cancer cells." (PMID 26204939, 2015). "It is possible that RUNX2 cooperates with HER1 and HER2 receptors in breast cancer cells and other cell types." (PMID 26404249, 2015). "The breast cancer cell line, MDA-MB-231, forms osteolytic bone lesions in mice, and Runx2 is required for this process." (PMID 22032690, 2011). "Reduction of RUNX2 levels by RNAi has only marginal effects on cell growth and expression of proliferation markers in MDA-MB-231 breast cancer cells." (PMID 21029421, 2010). "Immunohistochemical analysis was performed to evaluate the expression of vimentin, BMP-2, BMP-4, RANKL, Runx2, OPN, PTX3, and SDF-1, while Kaplan—Meier plots were used to assess their prognostic impact on overall survival in a dataset of 2976 breast cancer patients." (PMID 39859358, 2025). "Notably, the RUNX2 and matrix metalloproteinase 1 (MMP1) axis serves as a new marker for breast cancer diagnosis." (PMID 41511334, 2025). "We used a real-time transcriptional activity assay known as TRACER (TRanscriptional Activity CELL aRray) to measure the dynamic activity of six transcription factors involved in EMT signaling specific for breast cancer (TWIST1, SNAIL, HIF1a, RUNX1, RUNX2, and NOTCH1)." (PMID 38398186, 2024). "In our study, we found that NGR1 down-regulated RUNX2 to enhance MDA and Fe2+ levels and promote oxidative stress and iron ion accumulation in breast cancer cell lines, and NGR1 was also able to activate oxidative stress to inhibit cell growth and invasion in nasopharyngeal carcinoma." (PMID 38885076, 2024).